CDH1 (cadherin 1)
Diseases named in the same sentence as CDH1 in open-access papers (continued):
Sharing a sentence is not in itself a finding about the gene and the disease.
breast carcinoma (continued). "To conclude, miR-23a activated Wnt/β-catenin signaling and subsequently mediated the TGF-β1-induced EMT and tumor invasion in breast cancer by targeting CDH1." (PMID 29050223, 2017). "We reveal a new regulatory mechanism that miR-23a mediates the TGF-β1-induced EMT and tumor invasion in breast cancer by targeting CDH1 and activating Wnt/β-catenin signaling." (PMID 29050223, 2017). "Based on the regulatory mechanisms of genes zeb1 and cdh1 in the growth and development of breast cancer cells, we propose a kinetic model at the level of single cell." (PMID 28852133, 2017). "Fittingly, in mouse prostate tumor cells, FOXA1 and SNAIL2/SLUG reciprocally repress each other, and FOXA1 was reported to stimulate promoter activity of the epithelial marker gene CDH1 (coding for E-CADHERIN) in human breast cancer cells." (PMID 29155818, 2017). "Module 2 includes genes whose abnormal function has been directly associated with breast cancer, such as MAPK14, BRCA1, CDH1, HIF1A, CDKN2A and other members/regulators of the CDK family." (PMID 29093438, 2017). "Hereby we reported that miR-23a regulated TGF-β1-induced EMT and tumor metastasis in breast cancer cells by targeting CDH1 and subsequently activating Wnt/β-catenin signaling." (PMID 29050223, 2017). "Especially in breast cancer, the number of the studies confirmed the role of CDH1 -160C/A SNP in progression of cancer is equal to those that reject this role." (PMID 29285016, 2017). "We detected pathogenic mutations in nine of the 99 women in this group involving the ATM, BRCA1, CDH1, and CHEK2 genes, all of which have been associated with an increased risk of bilateral breast cancer in the previous studies." (PMID 28281021, 2017). "TFF3 participated in cancer invasion metastasis in breast cancer through repression of CDH1 mediated by STAT3." (PMID 28070169, 2017). "In conclusion, our results indicate that miR-23a directly decreases CDH1 expression in breast cancer cells." (PMID 29050223, 2017). "ESR1 (estrogen receptor alpha), GATA3 (GATA Binding Protein 3), and CDH1 (E-cadherin) are amongst the genes most down-regulated by Twist expression and shown to be involved in the progression of breast cancer earlier." (PMID 28086829, 2017). "Examples for hypermethylated breast cancer-associated genes are BRCA1, CCND2 (cyclin D2), ER, PR, CDH1 (E-cadherin), and many others." (PMID 29138528, 2017). "More importantly, we show that this occurs not only in a breast cancer cell line, but also in zebrafish embryos in which Zip10 stimulates Cdh1 down-regulation and cell autonomous migration responsible for gastrulation and anterior-posterior axis formation." (PMID 27274087, 2016). "The knockout of G9a restored CDH1 expression and results in the inhibition of cell migration and invasion in a model of breast cancer." (PMID 26905733, 2016). "LOXL2 even controls CDH1 by regulating H3K4me3 deamination, and LOXL2-E47 EMT factor plays a role in the repression of CDH1 in early metastasis colonization of breast cancer cells." (PMID 27285767, 2016). "SSX overexpression in a breast cancer cell line was shown to increase cell proliferation and repress the epithelial marker E-Cadherin (CDH1)." (PMID 27276714, 2016). "Among those significant mutations and CNVs associated with a CDH1 alteration, ERBB2 was the most well-known oncogene associated with high grade breast cancer." (PMID 27811364, 2016).
breast carcinoma (continued). "For CDH1, we performed a different analysis, to confirm that this gene has a strong gene-disease relationship with breast cancer." (PMID 27112211, 2016). "The familial CDH1 mutation has been identified in individual III‐7, a 69‐year old male with squamous cell skin cancer whose sister and mother both died of breast cancer." (PMID 27064202, 2016). "Cdh1 has been described as a potential tumor suppressor, since elevated Cdh1 levels inhibited breast tumor growth and depletion of Cdh1 induced proliferation of breast cancer cells." (PMID 26716651, 2016). "ST14/Prss14 is one of such genes: its expression was low in ERlow breast cancer cell lines, clustered together with CDH1 and its two inhibitors, SPINT1 and SPINT2." (PMID 27167193, 2016). "For the MCF10A to MDA-MB-231 comparison, MSigDB gene expression datasets defining breast cancer cell subtypes were used to select well-established EMT associated genes (VIM, CDH1, ZEB1) as central nodes to define an IPA gene association network." (PMID 26783963, 2016). "Inactivation of CDH1 by promoter hypermethylation has been observed in several types of cancers, including breast cancer, ovarian cancer and gastric cancer." (PMID 27067410, 2016). "Some clinical studies have reported that CDH1 expression is an indicator of poor prognosis or malignant potential in gastric cancer, breast cancer, and non-small cell lung cancer." (PMID 27600761, 2016). "miR-200b over-expression inhibited the transcriptional repressor ZEB2 and CDH1 in breast carcinoma cells." (PMID 27081085, 2016). "As expected, epithelial genes known to be inactivated during EMT in breast cancer cells, such as Cdh1 (E-cadherin), Ocln (Occludin), Epcam, Cldn7 (Claudin 7), Id1, Krt7, Esr1, Cav2, Dsp, Gata3, and Cadm1 were among the downregulated genes." (PMID 25674539, 2015). "We therefore compared the expression patterns of HMGA2 and CDH1 in human breast cancer cells using the GOBO tool." (PMID 25492890, 2015). "Genotype and allele frequencies of the selected SNPs in CDH1 and CTNNB1 and their associations with risk of breast cancer." (PMID 26285011, 2015). "It was initially known as the main susceptibility gene for gastric cancer of the diffuse type, but the excess of breast cancers of the lobular type in CDH1 families led researchers to identify it also as a susceptibility gene for invasive lobular carcinoma." (PMID 25848941, 2015). "This study indicated that the genetic polymorphisms of CDH1 and CTNNB1 were associated with breast cancer susceptibility and patients’ prognosis." (PMID 26285011, 2015). "Taken together, these data demonstrate that DNMT3B7 expression in breast cancer cell lines leads to hypermethylation and down-regulation of CDH1." (PMID 25607950, 2015). "Pardini and colleagues showed decreased CDH-1 mRNA expression in dogs with mammary carcinoma compared to normal tissue." (PMID 26370564, 2015). "The expression of EMT markers, including CDH1, CDH2, VIM, ZEB1 and ZEB2, is associated with poor prognosis of breast cancer patients." (PMID 26062653, 2015). "Our results point toward a concerted interdependence of MMPs, ITGB1, and CDH1 that is critical for breast cancer metastasis." (PMID 28721370, 2015). "In summary, this study indicated that the genetic polymorphisms of CDH1 and CTNNB1 were associated with breast cancer susceptibility and prognosis." (PMID 26285011, 2015). "Gene expression of ERα (ESR1), PGR, PRLR, GHR and CDH-1 was detected in normal mammary tissues and in all mammary neoplasms, except in one carcinoma." (PMID 26370564, 2015). "Out of the top ten mutated genes in the large breast cancer investigation of The Cancer Genome Atlas (TCGA), we found mutations in seven of these (PIK3CA, GATA3, MAP3K1, MLL3, CDH1, PTEN, TBX3)." (PMID 24998755, 2014).
breast carcinoma (continued). "KLF6-SV1, one of these splice variants, is able to drive breast cancer cells into an EMT-like phenotype, with loss of CDH1 and increased expression of CDH2 and FN1." (PMID 24429391, 2014). "Both in mouse mammary tumors and in human breast cancers, we observed elevation of Vim, Cdh2 (N-cadherin), Snai1 and Twist1 and downregulation of Cdh1 (E-cadherin) and Ocln." (PMID 25217618, 2014). "These included CDH1, the gene which encodes E-cadherin, and ERBB2, the gene which is amplified in 20-35% of breast cancer patients, both of which are known to be involved in breast tumorigenesis." (PMID 24641801, 2014). "The list of these genes includes not only a large number of known breast cancer genes (e.g. CDH1, CDH3, BMP4, MTAP, CDKN2B), revealed by previous studies using breast tumor tissues and breast cancer cell lines but also novel genes." (PMID 24885402, 2014). "Specifically, ZEB1 results downregulated in our breast cancer dataset compared to normal samples, while both the mir-200 family members and CDH1 are overexpressed." (PMID 25033876, 2014). "This is further supported by a positive correlation of MYB and CDH1 in breast cancer bone metastases, with both markers staining inversely to VIM (part ii)." (PMID 24283570, 2013). "MYB and CDH1 gene expression were found to correlate in human breast cancer cell lines and in primary human breast tumors and metastases." (PMID 24283570, 2013). "We overexpressed precursor miR-506 in MDA-MB-231 human breast cancer cell lines to monitor the expression of these target genes and CDH1 (an epithelial marker)." (PMID 23717581, 2013). "CTCF, also located on 16q22.1, has been found to act as a tumor suppressor in breast cancer through mechanisms similar to CDH1." (PMID 23717195, 2013). "Concomitantly, average expression level of those hypomethylated genes was lower after knockdown of CDH1, as well as in basal-like compared to luminal-like breast cancer subtypes (P <0.004)." (PMID 24367927, 2013). "Recently, a new claudin-low molecular subtype of breast cancer was identified that is characterized by low expression of tight junction and adherens proteins, including claudin-3, -4 and -7, and E-cadherin (CDH1), and enriched in stem-like and EMT features." (PMID 24009024, 2013). "MiR-9 is also overexpressed in MPNSTs and it has been previously demonstrated that miR-9 is upregulated in breast cancer cells and targets the E-cadherin gene (also named CDH1)." (PMID 23848554, 2013). "These include apparent decreases in caspase-3 and mmp-9, but increases in cadherin 1, thioredoxin reductase 2, and glutathione peroxidase 3 in the KO mammary carcinomas." (PMID 20932318, 2010). "On the other hand, CDH1 is commonly reported as downregulated in breast cancer, and thought to be methylated." (PMID 20799942, 2010). "Analysis of CDH1 methylation in breast cancers and other tumor types has shown that aberrant hypermethylation of CpG islands in CDH1 promoter region often occurs prior to invasion, indicating it to be an early event in tumorigenesis." (PMID 19751508, 2009). "Similar multi-gene correlations have linked metastases of breast cancer cells to sentinel lymph nodes with epigenetic alterations in CDH1 and RAR-β 2 and hypermethylation of ESR1, BRCA1 and CDH1 in breast LN metastases." (PMID 18638373, 2008).
breast carcinoma (continued). "During breast cancer progression, CDH1 gene methylation occurs in about 30% of the ductal carcinomas in situ, with a significant increase in invasive and metastatic lesions." (PMID 18702824, 2008). "SFN and CDH1 methylation have been reported in peripheral blood cells as well as in infiltrating leukocytes in breast cancer." (PMID 18702824, 2008). "Several reports have demonstrated the association either of the CDH1 gene methylation or the abnormal expression of E-cadherin in breast cancer progression." (PMID 16512896, 2006). "The hypermethylation of the promoter of the gene CDH1 was detected in 11 out of these 17 cases, including all six cases with familial breast cancer history." (PMID 16512896, 2006). "The E-cadherin gene (CDH1) maps, at chromosome 16q22.1, a region often associated with loss of heterozygosity (LOH) in human breast cancer." (PMID 16512896, 2006). "Recently, it was demonstrated that epigenetic silencing of the gene CDH1 by CpG island methylation of its promoter region, occurs in some human breast cancer cell lines, as well as in unselected primary breast cancer." (PMID 16512896, 2006). "In breast cancer, CDH1 promoter methylation has been reported in ~30% of in situ ductal carcinomas and increased substantially to nearly 60% in metastatic tumors." (PMID 16512896, 2006). "In concordance with increased E-cadherin (CDH1) expression shown in this cluster, an increase in (CDH1) mRNA (and CDH1–mediated cell–cell adhesion) has been shown previously in another breast cancer cell line after treatment with DOX." (PMID 15598611, 2004). "Furthermore, clustered CTCs in mammary tumors demonstrate greater metastatic efficiency than single disseminated tumor cells, with CDH1-mediated collective migratory behaviors that promote invasion and dissemination." (PMID 41459333, 2026). "Additionally, TWIST2 overexpression in breast cancers leads to the downregulation of CDH1 by repressing its promoter." (PMID 40869924, 2025). "Clinical trials specific to LBC or CDH1-mutant breast cancer are limited." (PMID 40757085, 2025). "However, decisions regarding surgery, such as nipple-sparing mastectomy, are complex because of the uncertain penetrance of CDH1 in breast cancer." (PMID 40366456, 2025). "In addition, phenethyl isothiocyanate inhibited breast cancer stem cells through the epigenetic reactivation of CDH1 (cadherin 1)." (PMID 39859345, 2025). "Furthermore, previous studies have reported that CDH1 inactivation promotes immune infiltration in breast cancer." (PMID 41404730, 2025).
breast carcinoma (continued). "In addition, our present analysis indicated that ZWINT expression levels were reduced in CDH1-mutant breast cancer patients compared to those with the wild-type." (PMID 40591167, 2025). "Due to the characteristic loss of E-cadherin expression in lobular cancers, several preclinical studies have utilized models of CDH1-defective breast cancer to explore whether new targets could be specifically applied to ILC." (PMID 39941785, 2025). "Lobular breast cancer is characterized by its lack of E-cadherin expression, which is directly linked to mutations or epigenetic silencing of the CDH1 gene." (PMID 40757085, 2025). "In addition, considering the poorly studied association between the number of tumor-infiltrating lymphocytes (TILs) and CDH1 methylation in breast cancer, we undertook a thorough analysis within our dataset." (PMID 38713384, 2024). "Besides, rare variants in other genes like ATM, CHEK2, CDH1, PALB2, RAD50, and RAD51C have been detected mainly in the breast cancer subgroup." (PMID 39148954, 2024). "Many pathogenic gene mutations common to breast cancer, such as Pten, Brca2, Atm, Cdh1, Chek2, Nf1, Arid1a, Pik3ca, and Esr1, revealed no alterations between NT2.5 and NT2.5-LM." (PMID 38717519, 2024). "Importantly, even if some ZEB1 target genes are shared between melanoma and breast cancer cell lines, such as CDH1 and other EMT genes, our study reveals cell type-specific effects of ZEB1, through the regulation of melanocytic lineage-specific genes." (PMID 38519642, 2024). "Loss of expression of E-cadherin (encoded by CDH1) impairs luminal and epithelial differentiation and induces an epithelial-to-mesenchymal transition (EMT) process, promoting invasion and metastasis in breast cancer." (PMID 39270819, 2024). "Therefore, by increasing CDH1 transcripts, compound 3 can modulate the epithelial to mesenchymal transition, contributing to the control of the progression of mammary tumor cells." (PMID 39339466, 2024). "Evidence of lowered levels of Cdh1 in tumors, and specifically in breast cancer, exists." (PMID 36797043, 2023). "CDH1 and PIK3CA mutation relate to metastasis in breast cancer patients." (PMID 37426414, 2023). "Finally, our results in Breast-AdenoCA also highlighted some genes that are specifically known to be frequently mutated in breast cancer, including PIK3CA, CDH1, GATA3, and MAP2K4." (PMID 38062391, 2023).